GALC (galactosylceramidase)
Description:
Hydrolyzes the galactose ester bonds of glycolipids such as galactosylceramide and galactosylsphingosine. Enzyme with very low activity responsible for the lysosomal catabolism of galactosylceramide, a major lipid in myelin, kidney and epithelial cells of small intestine and colon.
Tractability: Antibody: UniProt predicts a signal peptide or a membrane-spanning region.
Target class: Enzyme; Hydrolase
Gene: Protein-coding gene on chromosome 14 (87,837,820 to 87,993,665, reverse strand). Ensembl gene ENSG00000054983.
Subcellular location: Lysosome
Pathways (Reactome):
Metabolism: Glycosphingolipid catabolism
Gene Ontology:
Molecular function: galactosylceramidase activity
Biological process: galactosylceramide catabolic process; sphingolipid catabolic process; glycosphingolipid catabolic process
Cellular component: endolysosome lumen; lysosomal lumen; lysosome
Genetic constraint (gnomAD): Loss-of-function variants: 53 observed, 65.41 expected, observed/expected ratio (o/e) 0.81, 90% interval 0.65 to 1.02. The upper end of that interval is the gene's LOEUF score, 1.02, which puts it in group 4 of 6, group 1 being the genes least tolerant of losing a copy. Missense variants: 754 observed, 733.29 expected, observed/expected ratio (o/e) 1.03, 90% interval 0.97 to 1.09. Synonymous variants: 309 observed, 264.25 expected, observed/expected ratio (o/e) 1.17, 90% interval 1.07 to 1.28.
Gene-disease validity (ClinGen):
ClinGen rates the evidence that GALC causes each of these diseases.
Krabbe disease (autosomal recessive): Definitive. A lysosomal disorder that affects the white matter of the central and peripheral nervous systems.
Homologues: Orthologues: chimpanzee GALC (99% identical), macaque GALC (97% identical), pig GALC (88% identical), rabbit GALC (87% identical), guinea pig GALC (83% identical), mouse Galc (83% identical), rat Galc (82% identical), dog GALC (81% identical), tropical clawed frog galc (65% identical), zebrafish galca (61% identical), zebrafish galcb (61% identical), Caenorhabditis elegans C29E4.10 (32% identical).
Diseases named in the same sentence as GALC in open-access papers:
GALC is named in the same sentence as 113 diseases in open-access papers, as found by Europe PMC text mining. Sharing a sentence is not in itself a finding about the gene and the disease. The quoted sentences say what the papers report.
Krabbe disease (168 papers, 2005 to 2026). "Globoid cell leukodystrophy (GLD) is a genetic neurodegenerative disease caused by mutations in galactosylceramide β-galactosidase (GALC) that results in the accumulation of the cytotoxic sphingolipid, psychosine." (PMID 41578040, 2026). "Krabbe disease is an autosomal recessive, demyelinating disorder caused by mutations in the GALC gene." (PMID 40449593, 2025). "Regarding the lysosomal enzymes, two patients had heterozygous variants in GALC (Krabbe disease) and GLA (Fabry disease)." (PMID 40542290, 2025). "Krabbe disease is another demyelinating disease resulting from accumulation of galactosylceramides, which is caused by the decreased activity of galactosylceramidase (GALC)." (PMID 40076831, 2025). "Krabbe disease (KD), also known as globoid cell leukodystrophy, is a rare autosomal recessive neurodegenerative disorder caused by pathogenic variants in the GALC gene." (PMID 41278553, 2025). "Although the Thr112Ala variant is frequently found in newborns screened positive for Krabbe disease and several individuals have been identified with low or borderline GALC activity, its structural and pathogenic significance remains to be fully understood." (PMID 40943566, 2025). "Krabbe disease (KD), also known as globoid cell leukodystrophy, is a rare and severe autosomal recessive lysosomal storage disorder caused by mutations in the galactosylceramidase (GALC) gene." (PMID 40590240, 2025). "One patient, compound heterozygous for a pathogenetic variant and the p.(Arg184Cys), exhibited reduced GALC activity and a clinical course consistent with late‐onset Krabbe disease." (PMID 40391866, 2025). "Krabbe disease (KD) is an autosomal recessive disorder caused by a deficiency of galactosylceramidase, an enzyme tasked with degrading sphingolipids found in myelin." (PMID 41315317, 2025). "Krabbe disease (KD) is an autosomal recessive leukodystrophy caused by mutations in the GALC gene, which encodes galactocerebrosidase." (PMID 41278553, 2025). "Globoid cell leukodystrophy(GLD) is a rare hereditary inborn errorof metabolism due to recessive mutations that cause loss of functionof the enzyme galactosylceramidase (GALC)." (PMID 40603002, 2025). "As the homozygous Thr112Ala mutation in GALC causes Krabbe disease, we were interested in how this single amino acid substitution reduces the enzymatic activity of GALC." (PMID 40943566, 2025). "Globoid cell leukodystrophy or Krabbe disease (KD) (OMIM 245200) is an inherited demyelinating disorder caused by a deficiency of galactosylceramidase (GALC; EC 3.2.1.46)." (PMID 40449593, 2025). "Globoid cell leukodystrophy (GLD) is a fatal lysosomal storage disorder caused by a deficiency in the β-galactosylceramidase (GALC) enzyme, leading to severe demyelination and neurodegeneration, and often death before the age of 2 years." (PMID 40988335, 2025). "This reduces the substrate affinity of the enzyme, explaining on an atomic level how the Thr112Ala mutation in GALC causes Krabbe disease." (PMID 40943566, 2025). "Krabbe disease (KD) is a rare demyelinating disorder characterized by demyelination caused by mutations in the GALC gene, resulting in toxic accumulation of psychosine." (PMID 38558359, 2024). "Krabbe disease is a well‐known leukodystrophy caused by a defined mutation in the GALC gene in Cairn and West‐Highland white terriers." (PMID 38544400, 2024). "Lipid mediators from fatty acid oxidation have been shown to be associated with the severity of Krabbe disease (KD), a disorder linked to mutations in the galactosylceramidase (GALC) gene." (PMID 39000257, 2024).
Krabbe disease (continued). "Krabbe disease is caused by mutations in the GALC gene, leading to deficient activity of the enzyme galactocerebrosidase (GALC), which is responsible for the degradation of galactolipids in myelin." (PMID 39525762, 2024). "Krabbe disease (Kd) is a lysosomal storage disorder (LSD) caused by the deficiency of the lysosomal galactosylceramidase (GALC) which cleaves the myelin enriched lipid galactosylceramide (GalCer)." (PMID 39636943, 2024). "Krabbe disease is caused by mutations in the enzyme galactocerebrosidase (GALC) or its lipid-binding cofactor Saposin A, which prevents the degradation of galactosylceramide (GalCer) to ceramide." (PMID 39641585, 2024). "A deficiency of activity of lysosomal enzyme GALC in patients with the homozygous GALC mutation leading to Krabbe disease results in the rapid accumulation of galactosylsphingosine (or psychosine), a neurotoxic sphingolipid to neurons and myelinating cells." (PMID 38248833, 2023). "Krabbe disease is a rare neurodegenerative disease with an autosomal recessive character caused by a mutation in the GALC gene." (PMID 37892244, 2023). "Krabbe disease (KD; globoid cell leukodystrophy) (MIM: 245200) is an autosomal recessive LSD caused by a galactosylceramide-β-galactosidase (GALC, EC: 3.2.1.46) defect." (PMID 36713078, 2023). "In dogs with Krabbe disease, the effect of combined intravenous and intracerebroventricular administration of AAVrh10 encoding GALC was studied for both the peripheral and central nervous systems." (PMID 36835039, 2023). "More than 130 GALC pathogenic variants have been documented, of which over 95% are correlated with Krabbe disease." (PMID 37111381, 2023). "We also generated the first Krabbe disease-relevant induced pluripotent stem cells (K-iPSCs), and the fibroblast-derived K-iPSCs retained the GALC pathogenic variants." (PMID 37111381, 2023). "The sphingolipidoses Krabbe disease and metachromatic leukodystrophy are fatal early-onset demyelinating diseases caused by defects in the enzymes β-galactosylceramidase (GALC) and arylsulfatase A (ARSA) that degrade GalCer and sulfatide, respectively." (PMID 36996106, 2023). "Krabbe disease (KD) is a rare genetic lysosomal storage disorder caused by the mutation of the galactosylceramidase (GALC) gene." (PMID 36979906, 2023). "Of note, excess of GalCer due to the malfunction of galactosylceramidase causes demyelination in Krabbe disease." (PMID 36951944, 2023). "Among these, the contributions of GALC PPVs (rs138577661 and rs200607029), which are well-known variants of the Krabbe disease in the East Asian populations, was found to be considerable in our study." (PMID 37848935, 2023). "Krabbe disease, also known as globoid cell leukodystrophy, is a rare lysosomal storage disorder caused by deficiency of β-galactocerebrosidase (GALC) which is a catabolic enzyme of galactosphingolipids." (PMID 38273973, 2023). "In humans, genetic deficiency of the sphingolipid-metabolizing enzyme GALC leads to Krabbe disease, a neuroinflammatory degenerative disorder." (PMID 36012705, 2022). "Globoid cell leukodystrophy (GLD), or Krabbe disease, is an autosomal recessive neurodegenerative sphingolipidosis caused by genetic deficiency of the lysosomal hydrolase β-galactosylceramidase (GALC)." (PMID 36012705, 2022). "Krabbe disease is caused by a deficiency of the lysosomal galactosylceramidase (GALC) enzyme, which results in the accumulation of galactosylceramide (GalCer) and psychosine." (PMID 35789331, 2022). "Krabbe disease is caused by a deficiency of galactosylceramidase (GALC), a lysosomal acid hydrolase that catabolizes the lipids galactosylceramide (GalCer) and galactosylsphingosine (= psychosine)." (PMID 35789331, 2022). "Krabbe’s Disease (KD), also known as Globoid Cell Leukodystrophy, is characterized by mutations in the GALC gene that encodes the lysosomal enzyme galactocerebrosidase." (PMID 35693884, 2022).
Krabbe disease (continued). "Krabbe disease patients have mutations in the GALC (galactosylceramidase) gene that result in loss of function of this lysosomal enzyme." (PMID 36003149, 2022). "In Krabbe disease, also known as globoid cell leukodystrophy, mutations in β-galactosylceramidase (GALC), a lysosomal enzyme responsible for the catabolism of myelin galactolipids, lead to the accumulation of its substrates galactocerebroside and psychosine." (PMID 35793314, 2022). "Krabbe disease (KD) is a neuropathic lysosomal storage disease caused by deficiency of the enzyme β-galactosyl-ceramidase (GALC)." (PMID 35620447, 2022). "First, we only examined astrocytes generated from donors with infantile onset Krabbe disease, and both donors were homozygous for the large ~30 kb deletion in GALC found in Caucasians that results in near complete loss of enzyme activity." (PMID 35921286, 2022). "Krabbe Disease (KD) is a lysosomal storage disorder characterized by the genetic deficiency of the lysosomal enzyme β-galactosyl-ceramidase (GALC)." (PMID 35620447, 2022). "Krabbe disease is a demyelinating neurodegenerative disorder caused by a deficiency of the enzyme lysosomal galactosylceramidase (GALC), which results in the accumulation of galactosylceramide and psychosine." (PMID 35789331, 2022). "Krabbe disease (KD; or globoid cell leukodystrophy) is an autosomal recessive lysosomal storage disorder caused by deficiency of the galactosylceramidase (GALC) enzyme." (PMID 35028271, 2022). "Globoid cell leukodystrophy (Krabbe disease) is a fatal neurodegenerative, demyelinating disease caused by dysfunctional activity of galactosylceramidase (GALC), leading to the accumulation of glycosphingolipids including psychosine." (PMID 35921286, 2022). "Krabbe disease (KD), also known as globoid cell leukodystrophy, is a rare autosomal recessive condition caused by mutations in the galactocerebrosidase (GALC) gene." (PMID 36341094, 2022). "Krabbe disease is caused by mutations in the GALC gene encoding galactosylceramidase (also known as galactocerebrosidase, GALC) that degrades galactosylceramide (GalCer) to galactose and ceramide." (PMID 36409725, 2022). "Krabbe disease is a demyelinating leukodystrophy caused by autosomal recessive mutations of the galactosylceramidase (GALC) gene rendering the lysosomal hydrolytic enzyme that is required for myelin turnover inactive." (PMID 34239416, 2021). "Bi-allelic mutations in GALC, encoding the lysosomal hydrolase galactosylceramidase, cause Krabbe disease." (PMID 34282843, 2021). "Due to the deficiency of galactosylceramidase in Krabbe disease, galactosylceramide cannot undergo normal digestion to ceramide." (PMID 35118033, 2021). "From these studies in the twitcher strain, we conclude that Ripk1 kinase function has no primary role in driving or compensating for the effects of GALC deficiency in Krabbe disease." (PMID 34172992, 2021). "Krabbe disease is a rare autosomal recessive neurodegenerative disorder resulting from mutations in the GALC gene, which encodes the lipid-degrading lysosomal enzyme β-galactocerebrosidase." (PMID 34056672, 2021). "Krabbe disease (KD) is a neurodegenerative leukodystrophy caused by mutations in the galactosylceramidase (GALC) gene, which encodes the lysosomal b-galactocerebrosidase enzyme involved in myelin turnover." (PMID 34900869, 2021). "Krabbe disease is a lysosomal storage disease that is caused by a deficiency in galactosylceramidase." (PMID 35118033, 2021). "The characteristic leukodystrophy of Krabbe disease is thought to result from the accumulation of the toxic lipid psychosine, a precursor of galactosylceramide, a substrate of the enzyme encoded by GALC." (PMID 34056672, 2021). "Currently, more than 70 GALC variants are associated with Krabbe disease (information collected on HGMD database—on 10th July 2020)." (PMID 32883051, 2020).
Krabbe disease (continued). "Krabbe disease (KD) is caused by a deficiency of galactosylceramidase (GALC), which induces demyelination and neurodegeneration due to accumulation of cytotoxic psychosine." (PMID 33097716, 2020). "Evidence of another potential mechanism of action of the 2-hydroxypropyl-β-cyclodextrin has been described against cytotoxic psychosine, which is a sphingolipid found at high and cytotoxic levels in Krabbe disease due to the GALC deficiency in the CNS." (PMID 33304924, 2020). "In the early 70s, it was discovered that Krabbe disease/globoid cell leukodystrophy was caused by deficiency in the enzyme β-galactosidase (GALC) that normally degrades galactosylceramide." (PMID 32808655, 2020). "Krabbe's disease (KD) is a lysosomal sphingolipidosis caused by mutations in the galactosylceramidase gene (GALC) leading to accumulation of the neurotoxic lipid galactosylsphingosine (or psychosine)." (PMID 33424556, 2020). "GALC encodes the enzyme galactocerebrosidase, and mutations in this gene cause Krabbe disease, a lysosomal storage disorder." (PMID 33002040, 2020). "Mutations in GALC underlie Krabbe disease, an autosomal recessive disorder in which psychosine accumulates in the brain." (PMID 33060681, 2020). "Krabbe disease (OMIM #245200) is caused by a deficiency of GALC (Galactosylceramidase), which leads to the accumulation of psychosine (galactosylsphingosine), a metabolite of galactosylceramide." (PMID 32351971, 2020). "Globoid cell leukodystrophy (GLD) is a neurodegenerative lysosomal storage disease (LSD) due to the inherited deficiency of β-galactosylceramidase (GALC)." (PMID 32850960, 2020). "Krabbe disease is caused by GALC deficiency, leading to accumulation of cytotoxic psychosine, demyelination, and neurodegeneration." (PMID 33097716, 2020). "Mutations in ASAH1 (acid ceramidase) and GALC (galactosylceramidase) lead to Farber lipogranulomatosis and Krabbe disease, respectively." (PMID 32435656, 2020). "The earliest research efforts were to purify GALC, the enzyme deficient in patients with Krabbe disease." (PMID 32685352, 2020). "Krabbe disease is a rare autosomal recessive disorder caused by loss of function mutations in GALC, leading to deficiency of galactocerebrosidase, a lysosomal enzyme responsible for the degradation of galactocerebroside to ceramide and galactose." (PMID 30467211, 2019). "In Krabbe disease, the deficit of the β-galactocerebrosidase enzyme (GALC, E.C. 3.2.1.46) causes the accumulation of the lysosphingolipid β-galactosylsphyngosine, which is also known as “psychosine”, and is a major degradative product of myelin sheet turnover." (PMID 31091708, 2019). "Here we report the GALC mutations, a known and a novel one, in Chinese siblings with late-onset Krabbe disease." (PMID 31185936, 2019). "Krabbe disease (KD) is an autosomal recessive sphingolipidosis caused by the deficiency of the lysosomal hydrolase β-galactosylceramidase (GALC)." (PMID 31905906, 2019). "Accordingly, our data highlight that GALC-NSCs secrete enough active GALC enzyme to be taken up by Krabbe disease cells through the M6P receptor pathway and rescue deficiencies in enzyme levels." (PMID 31132746, 2019). "Krabbe disease (also known as globoid cell leukodystrophy) cause by a deficiency of the enzyme β-galactocerebrosidase (galactosylceramidase, GALC)." (PMID 31185936, 2019). "Krabbe disease is a rare lysosomal storage disorder caused by a defect in the galactosylceramidase (GALC) enzyme, rendering it unable to break down galactolipids which are abundant in the brain." (PMID 33072985, 2019). "For example, Krabbe disease is caused by loss of galactocerebrosidase (GALC) which is responsible for the removal of the terminal galactose from the glycosphingolipid galactocerebroside (GalCer)." (PMID 29323104, 2018).